PSMD9 (proteasome 26S subunit, non-ATPase 9)
Description:
Acts as a chaperone during the assembly of the 26S proteasome, specifically of the base subcomplex of the PA700/19S regulatory complex (RC). During the base subcomplex assembly is part of an intermediate PSMD9:PSMC6:PSMC3 module, also known as modulator trimer complex; PSMD9 is released during the further base assembly process.
Synonyms: p27; Rpn4
Tractability: PROTAC: ubiquitination databases record sites on it; its protein half-life has been measured.
Gene: Protein-coding gene on chromosome 12 (121,888,726 to 121,918,297, forward strand). Ensembl gene ENSG00000110801.
Subcellular location (Human Protein Atlas): Cytosol; Plasma membrane
Pathways (Reactome):
Metabolism of proteins: Proteasome assembly
Gene Ontology:
Molecular function: protein binding; bHLH transcription factor binding; transcription coactivator activity
Biological process: proteasome regulatory particle assembly; negative regulation of insulin secretion; positive regulation of DNA-templated transcription; positive regulation of insulin secretion; ubiquitin-dependent protein catabolic process
Cellular component: cytosol; proteasome regulatory particle, base subcomplex; cytoplasm; nucleus; proteasome regulatory particle
Genetic constraint (gnomAD): Loss-of-function variants: 21 observed, 22.81 expected, observed/expected ratio (o/e) 0.92, 90% interval 0.65 to 1.33. The upper end of that interval is the gene's LOEUF score, 1.33, which puts it in group 5 of 6, group 1 being the genes least tolerant of losing a copy. Missense variants: 250 observed, 264.97 expected, observed/expected ratio (o/e) 0.94, 90% interval 0.85 to 1.05. Synonymous variants: 92 observed, 97.06 expected, observed/expected ratio (o/e) 0.95, 90% interval 0.8 to 1.13.
Homologues: Orthologues: chimpanzee PSMD9 (99% identical), macaque PSMD9 (97% identical), dog PSMD9 (92% identical), pig PSMD9 (89% identical), rabbit PSMD9 (86% identical), rat Psmd9 (86% identical), guinea pig PSMD9 (86% identical), mouse Psmd9 (84% identical), tropical clawed frog psmd9 (61% identical), zebrafish psmd9 (52% identical), Drosophila melanogaster CG9588 (39% identical), Caenorhabditis elegans psmd-9 (30% identical).
Diseases named in the same sentence as PSMD9 in open-access papers:
PSMD9 is named in the same sentence as 31 diseases in open-access papers, as found by Europe PMC text mining. Sharing a sentence is not in itself a finding about the gene and the disease. The quoted sentences say what the papers report.
breast carcinoma (7 papers, 2014 to 2024). "For example, low PSMD9 expression is associated with relative tumor radiosensitivity in breast cancer." (PMID 38745188, 2024). "High expression of PSMD9 was associated with post-radiotherapy recurrence in cervical and breast cancer, and endogenous PSMD10 interacted with GRP78 to regulate endoplasmic reticulum stress, which might provide a therapeutic target for homocysteine-induced liver injury." (PMID 37349676, 2023). "Low expression of PSMD9 was discussed as a biomarker to assess patients’ suitability for radiation therapy in breast cancer, since cells with low expression were more vulnerable for radiation treatment." (PMID 35311102, 2022). "We performed Western blot analyses to confirm that our antibody recognised a protein of the appropriate size for PSMD9 (~25 kDa) in breast cancer cell lines." (PMID 24673853, 2014). "Our aim was to further analyse the relevance of 26S proteasome expression, focussing specifically on the PSMD9 subunit, in the largest clinical cohort to date, and to investigate the functional role of PSMD9 in radio-sensitivity in breast cancer cell lines." (PMID 24673853, 2014). "In support of this, reduction of PSMD9 expression using siRNA in breast cancer cell lines in vitro sensitized cells to radiotherapy." (PMID 24673853, 2014). "PSMD9 function was examined in breast cancer cell lines MCF7 and MDA-MB-231 using siRNA knock-downs and colony forming assays after irradiation." (PMID 24673853, 2014). "In order to determine whether PSMD9 expression was functionally associated with response to RT, we manipulated PSMD expression using siRNA in breast cancer cell lines and assessed sensitivity to RT in vitro." (PMID 24673853, 2014). "Next, we performed colony-forming assays with breast cancer cell lines representative of both luminal A (MCF7) and the basal (MDA-MB-231) subtypes after transfection with PSMD9-targeting siRNA, or control, and after different doses of radiation from 0 to 10 Gy." (PMID 24673853, 2014). "In breast cancers, we found PSMD9 expression to correlate with outcome only in patients treated with RT, indicating that PSMD9 represents a RT predictive marker rather than a simple prognostic marker for LR." (PMID 24673853, 2014).
diabetes (4 papers, 2011 to 2015). "In transgenic mice with pancreatic overexpression of the homologous of PSMD9, it has been shown that the increased dose of the PSMD9 protein is causing insulin deficiency and diabetes as well as hypertriglyceridemia." (PMID 21554682, 2011). "Since PSMD9 is a coactivator of insulin gene transcription, and in pancreatic overexpression of transgenic mice cause diabetes, PSMD9 variants may contribute to T2D as well as to obesity, overweight status and visceral obesity." (PMID 23282078, 2013). "Similarly, since PSMD9 is a coactivator of insulin gene transcription, and in pancreatic overexpression of transgenic mice cause diabetes, PSMD9 variants may contribute to T2DM as well as to obesity." (PMID 25928419, 2015). "The gene of Proteasome Modulator 9 (PSMD9) lies in the NIDDM2 region and is implicated in diabetes in mice." (PMID 21496327, 2011). "Furthermore, overexpression in transgenic mice of the coactivator Bridge-1, homologous of PSMD9, results in elevated triglyceride levels in Bridge-1/PSMD9 with severe diabetes compared to non-transgenic control mice." (PMID 21554682, 2011).
Obesity (4 papers, 2013 to 2023). Accumulation of substantial excess body fat. "Proteasome modulator 9 (PSMD9) gene was reported to be responsible for the linkage to obesity and obesity-associated phenotypes (waist circumference, overweight status) at the locus 12q24." (PMID 25928419, 2015). "Further supporting this, a small GWAS linked PSMD9 to obesity and T2D." (PMID 37000167, 2023). "The aim of the present study is to identify whether PSMD9 IVS3+nt460, IVS3+nt437, and 197G single nucleotide polymorphisms (SNPs) may be linked to maximum lifetime obesity, maximum lifetime overweight status and visceral obesity measured by waist circumference in an Italian family dataset." (PMID 23282078, 2013).
Hypercholesterolemia (3 papers, 2011 to 2015). An increased concentration of cholesterol in the blood. "The impact of proteasome modulator 9 (PSMD9) gene within the chromosome 12q24 locus on hypercholesterolemia and contribution to cardio- and cerebrovascular events and inflammation may be high." (PMID 23039238, 2012). "Proteasome Modulator 9 (PSMD9) lies in the 12q24 locus and is in linkage with MODY3, type 2 diabetes (T2D), microvascular and macrovascular pathology, carpal tunnel syndrome, and hypercholesterolemia in Italian families." (PMID 21871126, 2011).
Depression (2 papers, 2015). "The logistic regression model supports the role of the PSMD9 coding variant rs14259 (E197G A>G) for a significant association with insomnia, considering anxiety or depression as a covariates." (PMID 26166263, 2015). "PSMD9 SNP rs1043307/rs14259 (E197G-A>G) plays a role in anti-depressant therapy response, depression and schizophrenia." (PMID 26166263, 2015). "The Chi-square statistics reveals a significant association of PSMD9 SNP rs74421874 (IVS3+nt460G>A) and SNP rs3825172 (IVS3+nt437C>T), independently, with insomnia using anxiety as covariate (p-value = 0.029), but not using depression as covariate (p-value = 0.10)." (PMID 26166263, 2015).
glioma (2 papers, 2021 to 2023). A benign or malignant brain and spinal cord tumor that arises from glial cells (astrocytes, oligodendrocytes, ependymal cells). "Initially, differential expression analysis of PSMD9 was performed on glioma tissues of different grades, which revealed that increased protein expression of PSMD9 is associated with higher glioma grade." (PMID 37485655, 2023). "According to the TIMER2 database (glioma tissues, n = 153; adjacent normal tissues, n = 5), PSMD9/10/13/14 mRNA expression levels were significantly increased in GBM, while PSMD1 mRNA expression levels were decreased in GBM tissues." (PMID 37485655, 2023). "The differential expression of PSMD9 in GBM cell lines and glioma tissues of different grades was confirmed using western blotting and IHC." (PMID 37485655, 2023). "In this study, our objective was to analyse whether SMB6, PSMD9, UBB, PSMD12, PSMB10, PSMA5, and PSMD14 are independent prognostic factors for glioma." (PMID 34868920, 2021).
Hypertension (2 papers, 2011 to 2015). The presence of chronic increased pressure in the systemic arterial system. "Further, as PSMD9 is linked to T2D, it should be screened to identify any inheritance contributing factors to the T2D-associated phenotypes, of which hypertension is a major player." (PMID 21871126, 2011). "We conclude that the PSMD9 gene and/or any variant in linkage disequilibrium with the SNPs studied contribute to the linkage to hypertension within our family dataset." (PMID 21871126, 2011). "In the present study, we aimed at testing the PSMD9 IVS3+nt460, IVS3+nt437, E197G T2D risk SNPs for linkage with elevated blood pressure and/or hypertension in our 200 Italian T2D families." (PMID 21871126, 2011). "Given the reported linkage data of PSMD9 within the locus 12q24, and the evidence of linkage with microcirculation within the same locus, PSMD9 is a candidate gene for hypertension." (PMID 21871126, 2011). "Our analysis show that the PSMD9 IVS3 +nt460 A > G and +nt437 C > T and exon 5 E197G A > G SNPs studied and/or any variants in LD with them are in linkage with elevated blood pressure/hypertension in our 200 Italian families." (PMID 21871126, 2011).
Nephropathy (2 papers, 2011 to 2015). A nonspecific term referring to disease or damage of the kidneys. "We recently published that the PSMD9 IVS3 + nt460 A > G, IVS3 + nt437 C > T and E197G A > G T2D risk SNPs are linked to T2D-nephropathy as well as to macrovascular pathology." (PMID 21554682, 2011). "PSMD9 is in linkage with type 2 diabetes (T2D), T2D-nephropathy and macrovascular pathology in Italian families and PSMD9 rare mutations contribute to T2D." (PMID 21554682, 2011).
pancreatic ductal adenocarcinoma (2 papers, 2023). An infiltrating adenocarcinoma that arises from the epithelial cells of the pancreas. "In pancreatic ductal adenocarcinoma patients, high levels of PSMD6, PSMD9, PSMD11, and PSMD14 are associated with a lower rate of survival." (PMID 36934426, 2023). "In another study, the expression of PSMD6, PSMD9, PSMD11, and PSMD14 was significantly associated with a decreased chance of survival in patients with pancreatic ductal adenocarcinoma." (PMID 37349676, 2023).
anxiety disorder (1 paper, 2015). A category of psychiatric disorders which are characterized by anxious feelings or fear often accompanied by physical symptoms associated with anxiety. "Significant associations were detected between the presence of anxiety disorders in comorbidity with MDD and PSMD9 rs1043307." (PMID 26624926, 2015). "In addition, we found a positive association between PSMD9 rs1043307 and the presence of anxiety disorders in comorbidity with MDD, although this result was not significant following correction for multiple comparisons." (PMID 26624926, 2015).
asthma (1 paper, 2013). "It would be of interest to study the role of PSMD9 in asthma and IgE-mediated disorders as well as in final adult height." (PMID 23282078, 2013).
atherosclerosis (1 paper, 2011). A disease characterized by the build-up of fatty material and calcium deposition in the arterial wall resulting in partial or complete occlusion of the arterial lumen. "Thus, one potential role of PSMD9 in the phenotypes associated with T2D and atherosclerosis could be related to a direct role in the pathogenesis of inflammation as an autoimmune process." (PMID 21554682, 2011).
Autoimmunity (1 paper, 2013). The occurrence of an immune reaction against the organism's own cells or tissues. "PSMD9 may play an inflammatory role in autoimmunity with pleiotropic effects." (PMID 23282078, 2013).
breast tumours (1 paper, 2014). "We show that low expression of the 26S proteasome subunit PSMD9 was significantly associated with reduced incidence of LR in breast tumours after adjuvant RT." (PMID 24673853, 2014). "Expression of PSMD9 was examined using immunohistochemistry in these 157 breast tumours, taking into account the proportion of tumour cells staining positively, and their intensity using the Allred system." (PMID 24673853, 2014).
coronary artery disease (1 paper, 2011). "We then screened 200 T2D siblings/families for PSMD9 +nt460A/G, +nt437C/T and exon E197G A/G single nucleotide polymorphisms (SNPs) and performed a non-parametric linkage study to test for linkage for coronary artery disease, stroke/TIA, macro-vasculopathy and macrovascular pathology of T2D." (PMID 21496327, 2011). "Recently, a study reported a significant linkage to coronary artery disease (CAD), myocardial infarction, stroke to the chromosomal locus 12q24, within the NIDDM2 locus in which PSMD9 is located." (PMID 21496327, 2011).
hepatocellular carcinoma (1 paper, 2024). A malignant tumor that arises from hepatocytes. "However, the role and mechanism of PSMD9 in hepatocellular carcinoma (HCC) progression remain largely unclear." (PMID 38745188, 2024).
insomnia (1 paper, 2015). A sleep disorder characterized by difficulty in falling asleep and/or remaining asleep. "PSMD9 rs74421874 (IVS3+nt460-G>A), rs3825172 (IVS3+nt437-C>T) and rs1043307/rs14259 (E197G-A>G) SNPs are linked to insomnia in our Italian families." (PMID 26166263, 2015). "Thus, PSMD9 mediating inflammation may also contribute to insomnia." (PMID 26166263, 2015).
mental disorder (1 paper, 2015). A disease that has its basis in the disruption of mental process. "Only one study has shown a putative role of proteasomal PSMA7, PSMD9 and PSMD13 genes in the susceptibility to an antidepressant response, and sparse data are available regarding the potential alterations in proteasome expression in psychiatric disorders such as MDD." (PMID 26624926, 2015).
Stroke (1 paper, 2011). Sudden impairment of blood flow to a part of the brain due to occlusion or rupture of an artery to the brain. "The aim of the present study was to determine whether the IVS3+nt460A/G, +nt437C/T and exon E197G A/G T2D risk (SNPs) of PSMD9 cause evidence for linkage with other T2D-associated phenotypes such as CAD, stroke/TIA, vasculopathy and macrovascular pathology of T2D in Italians." (PMID 21496327, 2011).
cancer (8 papers, 2010 to 2025). A tumor composed of atypical neoplastic, often pleomorphic cells that invade other tissues. "We further confirmed the difference in PSMD9 expression between adjacent cancer tissue and cancer tissue by analyses of the Gene Expression Omnibus (GEO) and the JP Project from the International Cancer Genome Consortium (ICGC-LIRI-JP)." (PMID 38745188, 2024). "We first analyzed the expression of PSMD9 in numerous cancers using The Cancer Genome Atlas (TCGA) data." (PMID 38745188, 2024). "The data showed that PSMD9 depletion impaired cancer cell survival after RT." (PMID 36632223, 2023). "Our findings highlight the molecular mechanism of PSMD9 in HCC progression and provide valuable information for cancer prognosis evaluation and treatment." (PMID 38745188, 2024). "PSMD9 expression was analyzed in cancer tissues and adjacent noncancerous tissues via immunohistochemistry and Western blotting." (PMID 38745188, 2024).
tumor (6 papers, 2014 to 2024). "We found that PSMD9 expression was positively associated with tumor size, American Joint Committee on Cancer (AJCC) grade and metastasis." (PMID 38745188, 2024). "The PSMD9 is overexpressed in tumor tissues and associated with cell proliferation, hostile tumor outcome, and resistance to the therapy." (PMID 36180558, 2022). "Next, our aim was to examine whether PSMD9 expression in tumours was associated with response to RT." (PMID 24673853, 2014). "Although the role of PSMD9 in many tumor types has been studied, there are few reports about the role and molecular mechanism of PSMD9 in HCC." (PMID 38745188, 2024). "In contrast, compared with the control cells, Huh7 cells overexpressing PSMD9 promoted tumor growth, as determined by the liver weight." (PMID 38745188, 2024). "Depletion of the MLXIPe/KHSRP/PSMD9 regulatory complex inhibited tumor growth and RT sensitization of bone mPCa xenograft in vitro and in vivo." (PMID 36632223, 2023). "PSMD9 knockdown combined with erlotinib treatment reduced the overall tumor volume and mass." (PMID 38745188, 2024). "Several studies have reported that PSMD9 is correlated with the development of many tumor types." (PMID 38745188, 2024). "The results showed that OE of PSMD9 partially reversed the inhibitory effect of panobinostat on GBM proliferation and attenuated the extension of the survival period of tumor‐bearing mice induced by panobinostat." (PMID 37485655, 2023). "The expression of 26S proteasome non-ATPase regulatory subunit 9 (PSMD9) is correlated with recurrence and radiotherapy resistance in several tumor types." (PMID 38745188, 2024). "Since different tumor suppressors and oncogenes are controlled by the Ub- and proteosome-mediated degradation, the CSN7A, UBAC1, PSMD9, and RNF40 may play important roles in the pathogenesis of the KIRC." (PMID 36180558, 2022). "A cut off of 1 was selected, thereby defining tumours with no staining for PSMD9 as negative, and those with any staining as positive." (PMID 24673853, 2014).
vasculopathy (1 paper, 2011). "Our study shows that the PSMD9 IVS3+nt460A/G, +nt437C/T and exon E197G A/G SNPs studied are in linkage with CAD, cerebrovascular events, vasculopathy, and macrovascular pathology." (PMID 21496327, 2011).
PSMD9 also shares sentences with these, for which no sentence is quoted: carpal tunnel syndrome (2 papers); Anxiety (1); cervical cancer (1); diabetic retinopathy (1); hypertriglyceridemia (1); infection (1); neuropathy (1); retinopathy (1); schizophrenia (1).